DIO3 (iodothyronine deiodinase 3)
Diseases named in the same sentence as DIO3 in open-access papers (continued):
Sharing a sentence is not in itself a finding about the gene and the disease.
Sepsis (3 papers, 2017 to 2025). Sepsis is defined as life-threatening organ dysfunction caused by a dysregulated host response to infection. "Our results provide insights into the mechanisms of Dio3 reactivation and its critical role in local metabolic alterations induced by sepsis, while also suggesting novel targets aimed at ameliorating tissue-specific metabolic disorders." (PMID 39877839, 2025). "Mechanistically, IL-6 and ROS synergistically sustained the phosphorylation of STAT3 during early sepsis, thereby initiating the activation of the Shh pathway, by which the binding of Gli1 is potentiated to the Dio3 promoter." (PMID 39877839, 2025). "The targeted inhibition of Dio3 restores TH responsiveness and ameliorates sepsis-induced metabolic disruption in skeletal muscles, which leads to preserved muscle mass." (PMID 39877839, 2025). "Early sepsis leads to significant upregulation of Dio3 in the skeletal muscles and lung tissues of septic rats." (PMID 39877839, 2025). "In in vivo study, we observed a notable upregulation of Dio3 expression in the lung and skeletal muscles during the incipient stages of sepsis." (PMID 39877839, 2025). "The targeted inhibition of Dio3 ameliorated sepsis-induced metabolic dysregulation in skeletal muscles." (PMID 39877839, 2025). "Given the vital role of TH in maintaining myofiber type, we demonstrate that Dio3 inhibition prevents sepsis-induced fast-to-slow myofiber conversion, which preserves skeletal muscles in a glycolytic phenotype." (PMID 39877839, 2025). "In this study, an in-depth elucidation of mechanisms involved in the activation of Dio3 was conducted, and the pivotal role of Dio3 in facilitating metabolic alterations in sepsis was delineated." (PMID 39877839, 2025). "In elucidating the mechanisms involved in Dio3 reactivation in the early stages of sepsis, we conducted RNA-seq analysis in C2C12 myoblasts following 4 h of LPS exposure." (PMID 39877839, 2025). "Collectively, the inhibition of Dio3 maintains the glycolytic phenotype, preserves muscle mass, and ameliorates the metabolic disruption induced by sepsis in skeletal muscles." (PMID 39877839, 2025). "Notably, the Shh/Gli1 pathway predominantly regulates Dio3 in skeletal muscles and lung tissues upon early sepsis." (PMID 39877839, 2025). "In addition, a robustly induced expression of Dio3 was detected in human skeletal muscle biopsy samples at the acute stage of sepsis, which is consistent with previous research." (PMID 39877839, 2025). "Hence, the balance between protein synthesis and proteolysis can be rectified by inhibiting Dio3, which may protect muscle mass against sepsis-induced muscle atrophy." (PMID 39877839, 2025). "Herein, we aimed to evaluate the central and peripheral expression of genes involved in the transport (MCT8/Slc16a2 and MCT10/Slc16a10), metabolism (Dio1, Dio2, and Dio3) and action (Thra and Thrb) of TH during NTIS induced by fasting or sepsis." (PMID 29118715, 2017). "Type 3 deiodinase (DIO3) is present in immune cells, but there is no description of its presence in patients with sepsis." (PMID 36835345, 2023). "In CLP-induced sepsis group, Dio1 expression was decreased by 49% (P < 0.05) and Dio3 expression did not change between CLP-induced sepsis and Sham groups." (PMID 29118715, 2017). "In the total hypothalamus, the expression of Slc16a2, Slc16a10, Dio3, and Thrb did not change in these two models fasting and CLP-induced sepsis." (PMID 29118715, 2017). "In contrast to the increase in Dio3 expression during fasting, we did not observe changes in Dio3 expression in the CLP-induced sepsis." (PMID 29118715, 2017).
basal cell carcinoma (2 papers, 2023 to 2025). A carcinoma involving the basal cells. "In murine models of basal cell carcinoma, Dio3 knockdown with concomitant increase in local T3 led to a five-fold decrease in tumour growth." (PMID 37741974, 2023). "Given the pivotal role of the Shh pathway in governing Dio3 regulation in basal cell carcinomas (BCC), we hypothesized that the activation of the Shh pathway may also remarkably contribute to the reactivation of Dio3 within an inflammatory milieu." (PMID 39877839, 2025).
diabetes mellitus (2 papers, 2016 to 2022). A metabolic disorder characterized by abnormally high blood sugar levels due to diminished production of insulin or insulin resistance/desensitization. "Since then, the induction of the cardiac activity of Dio3 has been found in models of pathological remodeling of the LV induced by aortic stenosis, chronic myocardial infarction, isoproterenol, and diabetes mellitus." (PMID 35742991, 2022).
Hydrocephalus (2 papers, 2018 to 2022). Hydrocephalus is an active distension of the ventricular system of the brain resulting from inadequate passage of CSF from its point of production within the cerebral ventricles to its point of absorption into the systemic circulation. "MR image analyses of adult Dio3–/– brains of both sexes also revealed a dysmorphic brain exhibiting reduced length and width, increased height, and severe hydrocephalus." (PMID 36166296, 2022). "Dio3–/– brain also exhibited severe hydrocephalus, with a 7-fold increase in ventricular volume affecting the full ventricular system." (PMID 36166296, 2022). "However, the reduced cerebellum and hydrocephalus of Dio3−/− mice is consistent with the reduced head circumference and hydrocephalus observed in Temple syndrome patients." (PMID 29921775, 2018).
Hyperglycemia (2 papers, 2025). An increased concentration of glucose in the blood. "Thus, targeted inhibition of Dio3 in skeletal muscles can be an effective method to treat stress-induced hyperglycemia." (PMID 39877839, 2025). "Furthermore, Dio3 and GLUT4 appeared to colocalize, suggesting a link between NTIS and hyperglycemia." (PMID 40141055, 2025).
Kagami-Ogata syndrome (2 papers, 2019 to 2020). "Similarly, human mutations affecting Dio3 imprinting result in Temple or Kagami-Ogata syndromes that impair brain function; however, whether this phenotype can be fully attributed to the altered dosage from the Dio3 locus is unclear." (PMID 31001205, 2019).
liver disease (2 papers, 2016 to 2023). "They found in both a test and validation cohort of human NAFLD, a decreased fT3/rT3 ratio during advanced liver disease accompanied by decreased DIO1 and increased DIO3 protein." (PMID 36892852, 2023).
meningioma (2 papers, 2015 to 2022). A generally slow growing tumor attached to the dura mater. "Expression of the corresponding onco- and tumor suppressor genes TRIM58, FAM84B, ELOVL2, MAL2, LMO3, and DIO3 were analyzed and scored by immunohistochemical staining and RT-PCR in samples of 111 meningioma patients." (PMID 35445910, 2022). "In conclusion, this is the first study reporting the expression of the oncogenes TRIM58, FAM84B, ELOVL2, and DIO3 in meningiomas and correlations with histology and prognosis." (PMID 35445910, 2022). "Recent in vitro analyses revealed a dose-dependent efficiency of DCT also in high-grade meningiomas, with specific DNA demethylation of several onco- or tumor suppressor genes (TRIM58, FAM84B, ELOVL2, MAL2, LMO3, DIO3), which have been hardly investigated in meningiomas yet." (PMID 35445910, 2022).
myeloid malignancies (2 papers, 2009 to 2020). "Of interest, the DIO3 gene was also found to be hypermethylated in B-cell, T-cell and myeloid malignancies, and lung cancer." (PMID 32807826, 2020). "As well as identifying genes showing aberrant DNA methylation in certain HN subtypes, we also detected six genes—DBC1, DIO3, FZD9, HS3ST2, MOS, and MYOD1—that were significantly hypermethylated in B-cell, T-cell, and myeloid malignancies." (PMID 19750229, 2009). "As well as genes predominantly methylated in certain HN subtypes, we also identified six genes, i.e. DBC1, DIO3, FZD9, HS3ST2, MOS and MYOD1, that were significantly hypermethylated in B-cell, T-cell and myeloid malignancies." (PMID 19750229, 2009).
osteosarcoma (2 papers, 2016 to 2022). A usually aggressive malignant bone-forming mesenchymal neoplasm, predominantly affecting adolescents and young adults. "In the case of the DIO3 gene, the alteration of its expression has been reported in other types of sarcomas, such as osteosarcoma and myxoid liposarcoma." (PMID 36555675, 2022). "It has previously been reported that MEG3 is a tumor suppressor gene, but RTL1 and DIO3 remain candidate genes of interest and have not been well studied in osteosarcoma." (PMID 26802029, 2016). "To evaluate the co-expression of imprinted genes and miRNAs at the 14q32 locus, we analyzed the expression of DLK1-DIO3 cluster genes (DIO3, DLK1, MEG3, and MEG8) and representative 14q32 miRNAs (miR-134, miR-154, and miR-382) in an independent set of 43 osteosarcoma tumor samples." (PMID 26802029, 2016). "We found that Dio3 and Rtl1, the paternally expressed genes, were dramatically decreased in the DMR hypomethylated samples but had no significant change in the hypermethylated samples, again consistent with the human osteosarcoma samples." (PMID 26802029, 2016).
breast tumors (1 paper, 2020). "Thus, we hypothesized that the loss of DIO3 expression in breast tumors could be a consequence of gene hypermethylation in the tumoral context." (PMID 32807826, 2020).
choanal atresia (1 paper, 2022). Choanal atresia (CA) is a congenital anomaly of the posterior nasal airway characterized by the obstruction of one (unilateral) or both (bilateral) choanal aperture(s), with clinical manifestations ranging from acute respiratory distress to chronic nasal obstruction. "Surviving neonatal and adult Dio3–/– mice also exhibited choanal atresia and cleft palate with varying severities." (PMID 36166296, 2022). "Adult Dio3–/– mice manifested choanal atresia, a blockage of the nasal passage that may impair suckling during neonatal life." (PMID 36166296, 2022).
colon cancer (1 paper, 2020). "Similarly, in colon cancer cells, DIO3 knockdown and consequent increases in T3 levels are associated with reduced cell proliferation and induction of differentiation." (PMID 32807826, 2020).
COVID-19 (1 paper, 2025). A disease caused by infection with severe acute respiratory syndrome coronavirus 2. "In the context of critical conditionsand highly inflammatory diseases such as COVID-19, there is an alteration in themetabolism of TH through the induction of iodothyronine deiodinase 3, a Se-dependentenzyme." (PMID 40532042, 2025).
diabetic cardiomyopathy (1 paper, 2016). Diabetic cardiomyopathy is a disorder of the heart muscle in people with diabetes. "It is now a well-understood phenomenon that animal models of heart diseases, such as ischemia, diabetic cardiomyopathy and hypertensive/hypertrophic HF result in increased Dio3, decreased MCT-10 (one of the important T3 transporters) along with fetal gene reexpression." (PMID 26981865, 2016).
heart failure (1 paper, 2016). Inability of the heart to pump blood at an adequate rate to meet tissue metabolic requirements. "The increased expression of the T3-degrading enzyme Dio3 in the failing heart provides the most likely explanation for the reduced TH-signaling and has emerged as a potential common denominator in the development of heart failure." (PMID 27014189, 2016). "One of the genes that is re-expressed as part of the fetal gene program in various models of cardiac hypertrophy and heart failure is the thyroid-hormone-inactivating enzyme, deiodinase type III (Dio3)." (PMID 27014189, 2016).
lung fibrosis (1 paper, 2020). "Expression changes of miRNAs within the Dlk-Dio3 regions alters WNT signaling and has been associated with lung fibrosis." (PMID 32218238, 2020). "In particular, miR-323a-3p, which is located in the Dlk-Dio3 region, has been demonstrated to attenuate lung fibrosis in bleomycin-injured mice." (PMID 32218238, 2020).
Miscarriage (1 paper, 2023). A pregnancy that ends at a stage in which the fetus is incapable of surviving on its own, defined as the spontaneous loss of a fetus before the 22th week of pregnancy. "The expressions of Dio2 and Dio3 were significantly down-regulated in villi of the miscarriage group compared to the ETP group." (PMID 37968664, 2023). "In addition, Dio2 and Dio3 presented lower expression at the mRNA level in the villi of miscarriage cases." (PMID 37968664, 2023). "In miscarriage group, the gene expression of Dio2, Dio3, TTR and THRα, but not THRβ, MCT8 and OATP1A1, were downregulated." (PMID 37968664, 2023).
pancreatic tumors (1 paper, 2025). "IL-6-STAT3 signaling not only controls Shh activation in pancreatic tumors, but also exerts a strong correlation with Dio3 expression." (PMID 39877839, 2025).
serous ovarian cancer (1 paper, 2021). "The knockdown of DIO3 in high-grade serous ovarian cancer leads to a decrease in the Warburg effect and carcinogenic signal transduction and tumor growth inhibition." (PMID 34496868, 2021).
steatosis (1 paper, 2021). Increased lipid within the cytoplasm of cells. "Amongst the 13 genes, eight (DIO1, GPX2, SEPHS2, SELENOK, SELENOS, SELENOT, SELENOF, and SELENOW) had higher, and five (DIO3, GPX1, SELENON, SELENOO, and TXNRD3) had lower expression in steatosis." (PMID 34869521, 2021). "Similarly, four out the five genes with lower expression in steatosis also had lower expression in NASH (SELENOO, SELENON, DIO3, and TXNRD3) compared to HC." (PMID 34869521, 2021).
tumor (42 papers, 2014 to 2025). "Disturbed expression of type 3 deiodinase (DIO3), the main TH-inactivating enzyme, occurs in several human neoplasms and has been associated with adverse outcomes." (PMID 32807826, 2020). "On the other hand, DIO3 is upregulated in PTC tissues, and elevated DIO3 levels are associated with the BRAFV600E mutation, larger tumour size, and metastasis." (PMID 40647171, 2025). "DIO3 (Iodothyronine Deiodinase 3) plays a major role during embryogenesis and has also been described to promote cancer development by inhibiting tumor-suppressive actions of thyroid hormone T3 in several malignancies such as ovarian, lung, or prostate cancer." (PMID 35445910, 2022). "Recent studies have shown that increased expression of DIO3 enhances tumor proliferation suggesting the possible roles of deiodinases as cancer makers and potential modulators of tumor progression." (PMID 33935708, 2021). "We have previously reported that DIO3 mRNA and activity levels are increased in papillary thyroid cancer (PTC), which are associated with larger tumor size, and the presence of lymph node and distant metastasis at diagnosis." (PMID 32807826, 2020). "Furthermore, increased DIO3 expression was significantly higher in very low/low-risk prognostic patients, hinting at a possible link between DIO3 levels and tumor progression prognosis." (PMID 39170648, 2024). "Finally, we conducted a gene network analysis of the DEFA gene and found that there were tumor-suppressor-related genes associated with DEFA, including FGF21 and ITLN1, as well as tumor-promoting genes associated with DEFA, including GNB3, CRB2, DIO3, HPD, and Dll3." (PMID 41009818, 2025). "Our study investigated DIO3 expression in GIST samples and its correlation with tumor characteristics, aiming to enhance prognostic stratification and personalized treatment strategies." (PMID 39170648, 2024). "In order to investigate methylation-dependent RNA expression changes, some components of the DLK1-DIO3 cluster, such as DIO3, SNORD113-5, SNORD113-7, SNORD114-9, and miR-889, were randomly selected to analyze their expression levels in matched normal-tumor samples." (PMID 29435111, 2018). "However, comparison of the tumor-adjacent gastric tissue between HP+ and HP- patients revealed 8 differentially methylated CpG sites located within 7 genes (CCNA1, CSPG2, DAB2IP, DIO3, FLT1, STAT5A and TWIST1)." (PMID 24674026, 2014).
cancer (31 papers, 2012 to 2024). A tumor composed of atypical neoplastic, often pleomorphic cells that invade other tissues. "The dysregulation of DIO3 and its associated ncRNAs within this locus highlights their potential as diagnostic markers and therapeutic targets in cancer management." (PMID 39170648, 2024). "In various other cancers, DIO3 has been implicated through its association with the imprinted delta-like non-canonical Notch ligand 1 (DLK1)-DIO3 locus." (PMID 39170648, 2024). "In particular, studies have demonstrated that the local control of THs signaling provided by the regulation of DIO3 activity is associated with cancer development, progression, and recurrence." (PMID 32807826, 2020). "The high co-transcription between miR-1247-5p and DIO3 across all cancer types suggests that they share the same promoter by divergent transcription (rmeta = 0.62 [0.55–0.69], FDR = 7.4 × 10−13)." (PMID 34572448, 2021). "Among 38 divergent miRNA-host pairs, only miR-1247 and DIO3 showed strong coexpression across all cancer types (rmeta = 0.62 [0.55–0.69], FDR = 7.4 × 10−13)." (PMID 34572448, 2021). "Alternatively, the distinct pattern of expression could be the result of DIO3 regulation or related to the cancer-type specific methylation signature." (PMID 32807826, 2020). "In the lung cancer cohort, 13 retrogenes showed decreased expression in cancer (RPL13AP17, HNRNPA1P33, SIRPAP1, AL136982.4, AL136452.1, AC084880.1, HMGN2P15, CDC20P1, AC022217.1, DIO3, HMGB3P10, BET1P1, and TMED10P2)." (PMID 33478113, 2021).
cardiac disease (4 papers, 2016 to 2018). "There is speculation that the myocardium senses hypoxia in various heart diseases and is programmed to activate type 3 iodothyronine deiodinase (DIO3) which converts T4/T3 to inactive forms of THs, lowering tissue T3 levels in response." (PMID 28004791, 2016).
cardiovascular disease (3 papers, 2018 to 2022). "Seven of these DMPs (25%) could be allocated to a gene that was previously associated with cardiovascular diseases (HDAC4, IGF2BP3, CASZ1, SDK1, PCDHGA1, DIO3, PTPRN2)." (PMID 34895303, 2021).
neurodevelopmental disorder (3 papers, 2013 to 2022). A behavioral and cognitive disorder with onset during the developmental period that involves impaired or aberrant development of intellectual, motor, or social functions. "The sensitive epigenetic nature of the mechanisms controlling the genomic imprinting of Dio3 renders brain TH action particularly susceptible to disruption due to exogenous treatments and environmental exposures, with potential implications for the etiology of human neurodevelopmental disorders." (PMID 29921775, 2018).
metabolic disorders (1 paper, 2025). "Collectively, pharmacological blockade of the Shh pathway effectively inhibited the induction of Dio3 in tissues, ameliorated low T3 state, improved systemic glucose metabolic disorders, and preserved muscle mass." (PMID 39877839, 2025). "Our results clarify the critical role of Dio3 in local metabolic alterations and propose novel interventions targeting STAT3/Shh/Gli1 signaling aimed at ameliorating tissue-specific metabolic disorders under septic conditions." (PMID 39877839, 2025).
neurological disorders (1 paper, 2018). "The divergence between the TH states of the serum and the brain that occurs in Dio3−/− mice is of critical importance in the clinical context of neurological disorders." (PMID 29921775, 2018). "In the context of current paradigms, the present review also focuses on the imprinting of Dio3 in brain tissue, and explores its potential significance for brain development and neurological disorders." (PMID 29921775, 2018). "Given the broad spectrum of neurological traits affected by DIO3 deficiency and their relevance to human conditions, altered Dio3 imprinting appears as a potential epigenetic mechanism contributing to the developmental and non-genetic but heritable-etiology of neurological disorders." (PMID 29921775, 2018).